CCDC9B (coiled-coil domain containing 9B)
Synonyms: C15orf52; FLJ43339
Tractability: No criterion of Open Targets' tractability assessment is met for any kind of drug.
Gene: Protein-coding gene on chromosome 15 (40,331,452 to 40,340,939, reverse strand). Ensembl gene ENSG00000188549.
Subcellular location (Human Protein Atlas): Cytosol; Nucleoplasm
Gene Ontology:
Molecular function: RNA binding
Genetic constraint (gnomAD): Loss-of-function variants: 43 observed, 47.65 expected, observed/expected ratio (o/e) 0.9, 90% interval 0.71 to 1.16. The upper end of that interval is the gene's LOEUF score, 1.16, which puts it in group 5 of 6, group 1 being the genes least tolerant of losing a copy. Missense variants: 662 observed, 625.07 expected, observed/expected ratio (o/e) 1.06, 90% interval 0.99 to 1.13. Synonymous variants: 238 observed, 243.43 expected, observed/expected ratio (o/e) 0.98, 90% interval 0.88 to 1.09.
Homologues: Orthologues: chimpanzee CCDC9B (98% identical), macaque CCDC9B (94% identical), pig CCDC9B (76% identical), dog CCDC9B (74% identical), guinea pig CCDC9B (70% identical), mouse Ccdc9b (66% identical), rat Ccdc9b (62% identical), tropical clawed frog ccdc9b (22% identical), Caenorhabditis elegans C10G8.8 (14% identical), zebrafish ccdc9b (14% identical). Paralogues in human: CCDC9 (21% identical).
Diseases named in the same sentence as CCDC9B in open-access papers:
CCDC9B is named in the same sentence as 6 diseases in open-access papers, as found by Europe PMC text mining. Sharing a sentence is not in itself a finding about the gene and the disease. The quoted sentences say what the papers report.
breast carcinoma (1 paper, 2025). "These genes, including NBPF12, CCDC9B, and GABRE (which encodes a subunit of the GABA receptor), are known to play roles in breast cancer progression." (PMID 41285961, 2025).
hepatocellular carcinoma (1 paper, 2023). A malignant tumor that arises from hepatocytes. "Low mRNA levels of NSUN7 in both hepatocellular cancer cohorts were also associated with lower expression of CCDC9B." (PMID 37173708, 2023).
liver cancer (1 paper, 2023). An epithelial or non-epithelial malignant neoplasm that arises from the liver. "Overall, all these data indicate that NSUN7 catalyzes the 5-methylcytosine methylation of the CCDC9B mRNA and that NSUN7 epigenetic inactivation induces the loss of these RNA modifications in liver cancer cells." (PMID 37173708, 2023). "We have also shown that the addition of the m5C modification in CCDC9B mRNA stabilizes the molecule, whereas the NSUN7 mediated epigenetic inactivation in liver cancer decreases CCDC9B mRNA half-life." (PMID 37173708, 2023). "Focusing in liver cancer, we have been able to show that this enzyme exerts its m5C RNA methyltransferase activity on mRNA, characterizing the transcript of coiled-coil domain containing 9B (CCDC9B) gene as a relevant target in hepatic cancer." (PMID 37173708, 2023). "Most importantly, proteomic analyses determined that CCDC9B loss impaired protein levels of its partner, the MYC-regulator Influenza Virus NS1A Binding Protein (IVNS1ABP), creating sensitivity to bromodomain inhibitors in liver cancer cells exhibiting NSUN7 epigenetic silencing." (PMID 37173708, 2023).
pancreatic ductal adenocarcinoma (1 paper, 2023). An infiltrating adenocarcinoma that arises from the epithelial cells of the pancreas. "C15orf52, also known as CCDC9B, has been identified as a hub gene of pancreatic ductal adenocarcinoma development in the weighted gene co-expression network analysis." (PMID 38074669, 2023).
teratozoospermia (1 paper, 2022). "Coiled-coil proteins were also found to be enriched in the network produced using STRING, thus, CCDC9B is a very promising candidate gene for teratozoospermia." (PMID 36140773, 2022).
cancer (1 paper, 2025). A tumor composed of atypical neoplastic, often pleomorphic cells that invade other tissues. "The methyltransferase NSUN7 is primarily recognized for its role in cancer, where it methylates the mRNA of CCDC9B (Coiled-Coil Domain Containing 9B) and reduces MYC expression." (PMID 41516134, 2025).